POU3F2 (POU class 3 homeobox 2)
Diseases named in the same sentence as POU3F2 in open-access papers (continued):
Sharing a sentence is not in itself a finding about the gene and the disease.
tumor (52 papers, 2012 to 2025). "Capsaicin can inhibit the activity of tumor associated NADH oxidase by suppressing the expression of domain transcription factor POU3F2, restricting tumor growth, and inducing apoptosis." (PMID 34639131, 2021). "In numerous putative targets of miR-490-3p, POU3F2 was selected due to a crucial pro-tumor effect in numerous cancers." (PMID 31920461, 2020). "Through its ability to modulate MAPK pathway activation and MITF expression, POU3F2 can suppress melanocytes differentiation and increase tumor metastasis." (PMID 27271588, 2016). "Inhibiting PI3K is shown to reduce tumor cell invasion through downregulating POU3F2." (PMID 32169117, 2020). "Moreover, POU3F2 was reported to transcriptionally repress T-cadherin, which is a tumor suppressor that is expressed at extremely low levels in several types of carcinomas." (PMID 27271588, 2016). "We identify tNOX as a new downstream target of POU3F2 and provide evidence that their positive relationship may explain the pro-tumor functions of POU3F2 in promoting cell proliferation, migration and invasion." (PMID 27271588, 2016). "POU3F2 has been shown to be responsive to MAPK pathway activation and to modulate the levels of microphthalmia-associated transcription factor (MITF) so as to suppress the differentiated melanocytic phenotype and to enhance tumor metastasis." (PMID 25395235, 2015). "It was described that POU3F2, SOX2, SALL2, and OLIG2 maintain the tumor-forming capability of these cells." (PMID 32634135, 2020). "POU class 3 homeobox 2 (POU3F2), which belongs to the class III POU factors, has been reported to expedite tumor cells proliferation or even promote tumorigenesis." (PMID 31920461, 2020). "Epigenome-wide mapping of chromatin states in GBMs identified four core transcription factors, such as POU3F2 (also called OCT7, BRN2), SOX2, SALL2, and OLIG2, which are able to reprogram differentiated tumor cells into GSCs8." (PMID 27934912, 2016). "Brn2 (POU3F2) is required for the development of endocrine tissues and neurosecretory neurons, and tumour-promoting effects have been described." (PMID 23666755, 2013). "Therefore, these target genes can also provide new directions for future tumor treatment, especially the five genes DLC1, LRFN5, NOVA1, POU3F2 and PRICKLE2 which were positively related to the overall survival time." (PMID 35578189, 2022). "Heatmap analysis of gene expression in adherent cells and stem‐like tumor spheres revealed a negative correlation between YY2 and stem‐related factors, including CD44, SOX9, SALL2, KLF15, OCT4 (also known as POU class 5 homeobox 1 or POU5F1), MYC, ASCL1, and POU3F2." (PMID 37300334, 2023).
cancer (25 papers, 2010 to 2025). A tumor composed of atypical neoplastic, often pleomorphic cells that invade other tissues. "Consistent with the previous association of tNOX expression with cancer cell growth, cell impedance measurements revealed that POU3F2 knockdown cells exhibited reduced cell growth compared to control cells." (PMID 27271588, 2016). "Recent work has focused on the association of POU3F2 expression with tumorigenesis, particularly aggressive cancer cell phenotypes." (PMID 27271588, 2016). "In contrast, capsaicin-suppressed POU3F2 or knockdown of POU3F2 both downregulates tNOX and affects the cancer phenotypes." (PMID 27271588, 2016). "Together, these previous findings support the idea that the transcriptional targets of POU3F2 contribute to aggressive cancer phenotypes." (PMID 27271588, 2016). "Based on these observations, both Pou3f2 and Mms22l might serve as cancer therapy targets, which could be aided by the mechanistic understanding of a possible interaction with Pelomonas." (PMID 37264412, 2023). "Interestingly, the downregulation of two genes from module 106 are associated with cancer cell phenotype switching: the microphthalmia-associated transcription factor (MITF) and the POU domain transcription factor POU3F2 (better known as BRN2)." (PMID 35631574, 2022). "Furthermore, simultaneous expressions of YB-1 and the other four (SOX2, POU3F2, OCT-4, and OLIG1) or five (SOX2, SALL2, OCT-4, POU3F2, and Bmi-1) transcription factors in YB-1 knockout cancer stem cells restored the stemness of YB-1 knockout cancer stem cells." (PMID 31375149, 2019). "Based on our novel results, for the first time, we report that capsaicin reduced cancer phenotypes through POU3F2-medaited tNOX downregulation, and overexpression of POU3F2 in AGS cells enhances tNOX protein expression that is associated with increased cell proliferation and migration." (PMID 27271588, 2016). "In addition to the abilities of POU3F2 to regulate neuron differentiation, accumulating evidence suggests that it is also involved in different types of cancer." (PMID 27271588, 2016). "In contrast, knockdown of POU3F2 downregulates tNOX, and the cancer phenotypes are affected." (PMID 27271588, 2016). "However, although POU3F2 seems to be important for cancer progression, little is known about the downstream genes and underlying mechanisms involved in these tumorigenic effects." (PMID 27271588, 2016). "c-MYC also regulates key transcription factors like SOX2, POU3F2, and OLIG2, driving the reprogramming of cancer stem cells (CSCs) and fueling cancer progression." (PMID 39430761, 2024). "Overexpression of the other four (SOX2, POU3F2, OCT-4, and OLIG1) or five (SOX2, SALL2, OCT-4, POU3F2, and Bmi-1) transcription factors in YB-1 knockout cancer stem cells generated similar results." (PMID 31375149, 2019). "In general, all those factors required for reprogramming cells, like POU3F2 (OCT7), Sox2, Sall2 and Olig2 are highly expressed in GBM and in more than 50% of cancers presenting high expression of these four transcription factors also CD133 is expressed." (PMID 29261132, 2017). "Taken together, our results show that overexpression of POU3F2 in AGS cells induces the upregulation of tNOX and the acquisition of aggressive cancer phenotypes, including increased cell growth, migration and invasion." (PMID 27271588, 2016). "Six multiple interacting TFs were found to have common functions between immune systems and cancer tissues, including CEBPGAMMA:NKX25:PLZF, CEBPGAMMA:PAX4:PLZF, CP2:NFY:PAX4, FOXJ2:PAX4:POU3F2, CEBPGAMMA:PAX4:PLZF, and FOXJ2:HNF3:PAX4." (PMID 20085649, 2010).
mental illness (2 papers, 2018 to 2021). "The transcription factor encoded by POU3F2 is a key regulator in multiple psychiatric disorders." (PMID 33539344, 2021).
neurodevelopmental disorder (2 papers, 2017 to 2025). A behavioral and cognitive disorder with onset during the developmental period that involves impaired or aberrant development of intellectual, motor, or social functions. "Loss-of-function mutations in the transcription factor POU3F2 have been identified in individuals with neurodevelopmental disorders." (PMID 40498903, 2025).
central nervous system disorder (1 paper, 2023). A disease involving the central nervous system. "Essential mutations alter enhancer activity through altered binding of key transcription factors (TFs) of embryonic neocortex, including ISL1, POU3F2, PITX1/2, and several SOX TFs, and are associated with central nervous system disorders." (PMID 36791193, 2023).
POU3F2 also shares sentences with these, for which no sentence is quoted: adenocarcinoma (7 papers); infection (4); developmental delay (3); cutaneous melanoma (2); lichen planus (2); metastatic tumors (2); neurological diseases (2); Alzheimer disease (1); Breast Invasive Carcinoma (1); CADASIL (1); ciliary dyskinesia (1); colorectal cancer (1); deafness (1); embryonic carcinoma (1); Erythema (1); heart diseases (1); hepatocellular carcinoma (1); hypogonadotropic hypogonadism (1); lentivirus infection (1); Leukoencephalopathy (1); lung diseases (1); macrencephaly (1); malignant glioma (1); neurodegenerative disease (1); Neurodevelopmental delay (1); neuroendocrine tumor (1); neurofibromatosis (1); non-small cell lung carcinoma (1); obsessive-compulsive disorder (1); osteosarcoma (1).
A further 7 diseases each share a sentence with POU3F2 in 1 paper.